IL6 (interleukin 6)
Diseases named in the same sentence as IL6 in open-access papers (continued):
Sharing a sentence is not in itself a finding about the gene and the disease.
infection (continued). "BMMCs responded to the infection by secretion of IL-6 protein in a MOI- and time-dependent manner." (PMID 38291037, 2024). "However, both genotypes showed increased levels of IL-6 mRNA following MHV-A59 infection compared to the mock groups." (PMID 39452742, 2024). "Indeed, IL-6 is the major inductor of the acute phase proteins and is involved in the control of neutrophil and monocyte responses following infection, thus confirming the increase of NLR and SII at D14." (PMID 39208074, 2024). "In the case of IL-6 (the most important mediator of the inflammation, stimulating the synthesis of acute phase protein), we observed its increase after infection with L. europaeus of both genotypes (8-fold change, p = 0.003 for GI.1 vs. control and 6.8-fold change, p = 0.004 for GI.2 vs. control)." (PMID 39273479, 2024). "Infection with the Beta variant had little impact on the production of Interferon γ-induced protein 10/IP-10 (C-X-C motif chemokine ligand 10/CXCL-10) and tumor necrosis factor-α (TNF-α), and resulted in a significant increase in Interleukin 6 (IL-6) levels." (PMID 38568894, 2024). "Compared with RV16 infection alone, IL-6 protein production was increased by cilomilast 2–3 folds." (PMID 39598462, 2024). "However, compared to serum IL-6, which is noticeably elevated in severe cases, serum IL-8 was easily detectable in mild infection." (PMID 38646483, 2024). "As a multifunctional cytokine, IL-6 is secreted by various cells, including lymphocytes, endothelial cells, and monocytes, and plays an important role in the body’s immune response against infections." (PMID 38355623, 2024). "We found that CETPi led to significantly lowered IL-6 levels at 72 hours after infection." (PMID 38646937, 2024). "Importantly, direct pharmacologic inhibition of FAO showed similar effects (suppressed IL-1β and IL-6 expression), with a decrease in pathologic lung damage in animal models of infection." (PMID 39007133, 2024). "Likewise, it has been observed that, despite the elevated levels of IL-6 in severe infections, this profile significantly differs from the inflammatory signatures associated with CAR -T cell-induced CRS." (PMID 38956649, 2024). "Infection with E. faecalis as well as catheter implantation are both known to stimulate IL-6 (64, –, 66), so this observation may suggest a role for HylA or HylB in tissue invasion and damage." (PMID 38842305, 2024). "SFTSV can infect macrophages in vivo and cause elevated both pro-inflammatory cytokines (such as IL-6 and IFN-γ) and anti-inflammatory cytokines (such as IL-10) in SFTSV-infected patients, and SFTSV infection of macrophages contributed to macrophage differentiation into the M2 phenotype." (PMID 38916398, 2024). "In addition, we also found that the expressions of CCL2, CXCL10 and IL-6 were significantly increased in the terminal stage of infection with RABV." (PMID 39273091, 2024). "All the groups showed a similar weight loss trend post-infection indicating that IL-6 deficiency had no impact on body weight loss during Cn infection." (PMID 39334365, 2024). "Infection‐mediated release of inflammatory cytokines, such as IL‐6 and TNF‐alpha, could further damage the disc, leading to disc degeneration and a pro‐inflammatory environment." (PMID 39398942, 2024). "For instance, IL-6 can modulate synaptic plasticity in neurons, gliotransmitter release in astrocytes, and promote microglia pro-inflammatory activity in case of injury or infection." (PMID 39425138, 2024). "Notably, PRUΔROP5 infection led to lower IL-6 expression in all three cell types compared with PRU infection." (PMID 39457045, 2024). "Likewise, IFN-independent activation of IFN-dependent signaling pathways such as Jak/Stat has also been documented, as seen during infection of monocytes via rerouting of IL-6 signaling." (PMID 38668515, 2024). "Compared with CRP and PCT, IL-6 has a higher predictive value for postoperative infections." (PMID 38504206, 2024).
infection (continued). "We next asked if silencing LONP1 could reduce inflammation during infection and found that IL-6 production was dampened upon S. Typhimurium infection by silencing LONP1 or pharmacologically inhibiting LONP1, or upon inhibition of complex I using Rotenone." (PMID 38263327, 2024). "Interestingly, we observed a decrease in the expression levels of TNF-α and IL-6 after 6 h of infection with 2 multiplicity of infection (MOI) Vv when pretreated with CGP57380." (PMID 38980024, 2024). "The efficiency with which AN_CH_37 treatment suppressed the pro-inflammatory response suggests that Mip supports potent stimulation of IL-1β, TNFα and IL-6, and thus may play an important role in host inflammatory pathology following infection." (PMID 38590438, 2024). "CRP is synthesized mainly in liver cells, there is growing evidence that CRP plays an important role in inflammatory processes and host response to infection, including the complement pathway, apoptosis, and the production of cytokines, particularly interleukin-6 (IL-6) and tumor necrosis factor-α." (PMID 39720727, 2024). "Indeed, activated dendritic cells, macrophages, and NK cells target the site of infection and secrete IL-1β, IL-6, and TNF-α, while activated CD4+ T and CD8+ T cells produce IFN-γ among other inflammatory cytokines that aggravate tissue damage." (PMID 38911850, 2024). "The GPNMB functions to reduce inflammation by increasing anti-inflammatory cytokines like IL10 and decreasing proinflammatory cytokines like TNFα, IL-6, and IL-12, which aid in response to lesions in the tissue or infection, and can be triggered by pathogens that are present in their environment." (PMID 39744066, 2024). "Through various signaling and metabolic pathways, ESAT6 participates in the inhibition of autophagy, in the triggering of necrosis, and in the stimulation of the production of cytokines IL-6, IL-1β, and IL-10 for the creation of a chronic proinflammatory background at a site of infection." (PMID 39591170, 2024). "Also, in immunized horses with an attenuated vaccine, the transcriptome analysis of immune responses in PBMCs after in vitro infection with AHSV revealed the up-regulation of genes of different cytokines such as IL-6, TNF, CXCL2 and IL-1β." (PMID 38396742, 2024). "IL-6 is a highly sensitive and specific indicator of infection-induced PTL." (PMID 38542370, 2024). "In line, IL-6 drives specific transcriptional programs of the antimicrobial gene in infected urothelial cells, effectively preventing epithelial invasion and ascending infection." (PMID 39766247, 2024). "Additionally, CRS, fever, PCT, IL-6, and CRP can serve as diagnostic indicators for infection in patients with fever." (PMID 38956649, 2024). "Continuously high concentrations of serum TNFα and IL-6 at the early infection course, as well as low IL-10, were detected in lnc-ip65−/− mice, suggesting that excessive inflammatory responses occurred and might contribute to the lethal pathogenesis." (PMID 38200007, 2024). "We observed an increase in IL-6 and IL-8 secretion in Cgyps1-11Δ-infected and a decrease in IL-6 and IL-8 secretion in wt-infected A-498, compared to uninfected A-498, from 6 h onwards post-infection (Fig. EV5C)." (PMID 39349750, 2024). "TLR4 involvement during the infection was also observed through mediating IL6 and TNFα." (PMID 39729468, 2024). "Furthermore, P1/7 induced NLRP3 inflammasome activation with increased protein expression of NLRP3 and caspase-1 at 9 h post-infection (hpi), leading to the production of inflammatory cytokines, including IL-1β and IL-6." (PMID 39334337, 2024). "IL-6 appears to be a reliable marker for assessing infection status before reimplantation." (PMID 39493345, 2024).
infection (continued). "The correlation between bioluminescent signals from whole mice or kidneys and various clinical parameters—including weight loss, kidney abscess scores, kidney CFU counts, as well as blood levels of S100A8/A9 and IL-6 analyzed on day 10 post-infection in both NMRI and C57BL/6 mice." (PMID 39204252, 2024). "In addition, MHV-A59 stimulated the production of IL-6 by wild-type BMDMs starting from 48 h post-infection, when the levels detected by infected cells were higher than those in uninfected controls." (PMID 39452742, 2024). "Furthermore, the STING inhibitor H-151 reduced IL-6 secretion and counteracted the pronounced differences in IL-6 secretion between Zc3hav1-/- mice and the control mice after infection with HSV-1 or injection of DMXAA." (PMID 39478149, 2024). "Thus, it seems likely that recruitment of these cells at day 7 post-infection with MHV68 contributes to the increase in IL-6 at this time point." (PMID 39338937, 2024). "The circulating cytokine (IL-6, IFNγ, and IP-10) levels were decreased at Day 4 after infection." (PMID 38474386, 2024). "The infection may also induce the release of cytokines such as interleukin-6 and tumor necrosis factor-alpha, which contribute to gastrointestinal symptoms." (PMID 39625915, 2024). "Similarly, Il-6 levels were lower in patients with cancer as compared to patients with infection (t = 2.81, p = 0.007), while Neu and CRP levels were similar to patients with cancer and the normal controls." (PMID 39338437, 2024). "In both systems, only TNF-α and IL-6 were substantially increased upon PAO1 infection." (PMID 38470050, 2024). "Indeed, Ad-shBDNF-infection enhanced the expression of tumor necrosis factor α (TNFα), and its regulated gene IL-6 in C2C12 myotubes and the muscle of MBKO mice." (PMID 39531828, 2024). "Although these factors play important roles in the progression of HIV disease, we speculate that this may be because IL2 and IL6 are markers of HIV early infection, while LTNPs and VPs in our study have lived with HIV for a longer time." (PMID 38799426, 2024). "Additionally, the markedly elevated level of IL-6 expression together with a high number of TRM T cells in the infected mouse brain was observed at 28 dpi following the initial infection." (PMID 39475775, 2024). "The analysis of cytokine levels in relation to the febrile stage and the type of infection revealed that IL-6 and IL-10 concentrations were elevated in Ph I from secondary infections compared to Ph I in primary infections (p = 0.005 and p < 0.001, respectively)." (PMID 39457019, 2024). "Indeed, heightened concentrations of IL-6 are commonly observed in cases of infection, and the evaluation of IL-6 levels in the bloodstream is effective in detecting the presence of an infection." (PMID 38337668, 2024). "Similarly, as a master regulator of inflammation, IL-6 is a typical pro-inflammatory factor that involves cytokine storm and inflammation responses central to the progression of infection diseases." (PMID 39114651, 2024). "For instance, novel JAK inhibitors and anti-IL-6 agents are being investigated for their ability to modulate immune responses with greater precision, potentially reducing the incidence of rejection and infection." (PMID 39200392, 2024). "Importantly, only tetrandrine significantly reduced IL-6 levels at 48 h post-infection by around 62%, whereas the effect of berberine was insignificant." (PMID 38664855, 2024). "Besides potential infection, the mechanical stretching of the cervix and uterus during labor can trigger an inflammatory response, leading to the release of cytokines such as IL-6." (PMID 39062232, 2024). "In the context of BRD, an acute increase in IL-6 may be beneficial for controlling infection, while a rapid decline in IL-6 might signal disease resolution and the prevention of uncontrolled inflammation." (PMID 38799472, 2024).
infection (continued). "In addition, IL-6, regulated by macrophages was proved to inhibit type I interferon signaling and, consequently, disease progression in the mouse infection models of TB." (PMID 38933114, 2024). "The greatest advantage of IL-6 is its ability to respond promptly after infection." (PMID 39411281, 2024). "Interestingly, deletion of the Apt1 flippase in Cn reduces the packaging of GXM into extracellular vesicles and impairs GXM synthesis whereas it reduces the production of IL-6 during infection and CNS colonization." (PMID 39334365, 2024). "Additionally, reduced IL-6 levels in treated mice confirmed the successful elimination of the infection." (PMID 39204252, 2024). "Blocking IL-6-IL-6R binding leads to acute phase response inhibition, impeding the α-1 antitrypsin (AAT) production and release which has a protective endogenous antiprotease and anti-inflammatory function, increasing the risk of infection." (PMID 39640429, 2024). "Additionally, the production of proinflammatory cytokines (TNF-α and IL-6), vital effectors mediating macrophage resistance againstBrucella infection, was augmented in the rBP26-immunized group." (PMID 38419498, 2024). "Therefore, we conducted this multicenter cohort study to determine and compare the IRs of infection in patients with RA treated with an interleukin-6 inhibitor (IL-6i) or a JAKi in real-world settings." (PMID 38792541, 2024). "Also, studies conducted on bovine mammary epithelial cells (MEC) indicate a rapid response to infection of the udder by pathogens expressed by IL-6 secretion." (PMID 38612339, 2024). "Another important discrepancy is that even though the IL-6−/− mice in the Li’s study showed increased brain fungal burden as the disease progressed, the Wild-type mice had minimal cryptococcal brain invasion throughout the duration of the infection." (PMID 39334365, 2024). "Moreover, it is worth noting that the concomitant use of glucocorticoids has been associated with severe adverse reactions and interruption of some biologics such as anti-TNF agents and anti–IL-6 agents, mainly owing to infection." (PMID 39886456, 2024). "Moreover, treatment with TAK-242 reduced M1_like and slightly increased M2_like macrophages and reduced pro-inflammatory cytokines levels including TNF, IL-1β and IL-6 in ECSparcl1-OE mice on day 20 after infection." (PMID 38762489, 2024). "Furthermore, the levels of TNF-α and IL-6 in the colonic culture supernatant of JMJD2D-/- mice on day 14 after infection were significantly more than those in the colonic culture supernatants of wild-type mice." (PMID 38905308, 2024). "IL-6 is an important mediator of the acute-phase response during infection." (PMID 38251210, 2024). "IL-6 is an important pro-inflammatory cytokine that is released during infection or tissue injury." (PMID 38456184, 2024). "In addition, IL-6 is utilized clinically to assess infection control and the activity of inflammatory disorders." (PMID 38882664, 2024). "Although the olanzapine concentration also increased post-infection, IL-6 may mainly affected the P450 enzyme system." (PMID 39077630, 2024). "IL-6 may be helpful in the earlier prediction of infection to some extent because it is elevated in infection before PCT and CRP." (PMID 38504206, 2024). "On the other hand, inflammatory factors such as IL-6 and TNF-α could affect the synthesis of albumin by hepatocytes, thus increasing the risk of infection and promoting the invasion and metastasis of tumors." (PMID 37495731, 2023). "Based on this, we hypothesize that IAV infection stimulates the expression of miR-141 in infected cells to regulate the expression profile of MxA as an interferon-inducible gene and STAT3, which is stimulated upon infection in response to IL-6 production." (PMID 37596622, 2023).
infection (continued). "Taken together, we can conclude that B cells provide a vital role in IL-6 production during the early phase of the infection and provide a protective role in the chronic stage of infection by attenuating proinflammatory cytokines in the lungs reducing fibrosis and other severe pathology." (PMID 37243059, 2023). "Infection-related neutrophil generation and activation, B-cell proliferation and differentiation, immunoglobulin synthesis, and T-cell proliferation and differentiation are all stimulated by IL-6." (PMID 37763669, 2023). "Early after infection, IL-6 conducts the synthesis of acute phase proteins (including C-reactive protein (CRP), fibrinogen, serum amyloid protein, and haptoglobin, among others) in the liver, which orchestrate the systemic host immune response independently of the site where infection takes place." (PMID 37818368, 2023). "•Genetic analyses have identified benefit of IL-6 inhibition in other infections." (PMID 36801374, 2023). "Notably, in line with the in vivo data, infection of MEFs with the G184R mutant virus resulted in significantly higher IL-6 secretion as compared to the wild-type strain, which is also reflected at the transcript level." (PMID 37582777, 2023). "Additionally, the compound appeared to perform immunomodulatory activity toward macrophages’ infection management due to the down expression of the pro-Leishmania cytokines IL-10 and IL-6." (PMID 37259353, 2023). "The major cytokines involved in the APR include interleukin-6 (IL-6), interleukin-1β (IL-1β), and tumor necrosis factor-α (TNF-α), and these cytokines produce the clinical signs associated with inflammation or infection stimulate other cells in the APR cascade, and activate the production of APPs." (PMID 36670767, 2023). "Additionally, in both age groups, a significant increase in the serum IL-6 concentration was observed after the first postoperative day, and this increase was more pronounced in patients diagnosed to have postoperative infections." (PMID 37189842, 2023). "Indeed, infected Acod1−/− mice expressed higher mRNA levels of Il6, IFNγ, Nos2 and Gbp1 than wild‐type controls in the lungs, but also in the spleen, after intratracheal infection." (PMID 36479617, 2023). "Another study showed that IL-6 was important for controlling P. aeruginosa early in infection." (PMID 37998353, 2023). "In addition to the robust release of pulmonary IL-6 and G-CSF, similar to infection with chs3Δ, YNB-U-grown cells also induced the expression of additional inflammatory molecules such as IL-1α, TNF-α, and the CCL class of chemokines." (PMID 37538303, 2023). "Interleukin-6 (IL-6) is a pleiotropic cytokine that coordinates host immune responses to infection." (PMID 37682929, 2023). "IL-6 is an important inducer of acute phase response and protection against infection." (PMID 36830933, 2023). "As we noticed a difference in early TNF-α and IL-6 production after infection with the two strains, we examined whether PPAR-γ activation could play a role in the expression of these cytokines." (PMID 37376550, 2023). "To determine whether this model elicits a pro-inflammatory response, similar to what has been shown previously using shorter infection times, we analyzed mRNA expression levels of IL-1β, IL-6 and CXCL8 (IL-8) along with protein levels of IL-8 in our model." (PMID 37432929, 2023). "However, at 24 h of infection with persister cells, a bi-modal trend was present in IL-6 and CXCL-8 with an overall increase in secretion, compared to 1.5 h, while IL-10 was at levels identical to uninfected macrophages." (PMID 36920189, 2023). "Given the sharp decline in cytokine levels over the critical first 7 days after delivery, we further interrogated the temporal association of MCP-1 values with clinically suspected prenatal infection and IL-6 values, as well as CRP levels, with clinically diagnosed postnatal infection." (PMID 37606448, 2023).